NTRK2 (neurotrophic receptor tyrosine kinase 2)
Diseases named in the same sentence as NTRK2 in open-access papers (continued):
Sharing a sentence is not in itself a finding about the gene and the disease.
cancer (continued). "Although NTRK-associated fusions are significant in various cancers and have led to the development of targeted therapies, such as larotrectinib and entrectinib, the specific molecular impact of atypical PRUNE2::NTRK2 fusion remains unclear." (PMID 41323367, 2025). "Neurotrophic tyrosine receptor kinase 1, 2, and 3 (NTRK1, NTRK2, and NTRK3) genes encode for three tyrosine kinase receptors (TRKA, TRKB, and TRKC, respectively) and act as oncogenic drivers in a well-defined subgroup of cancers." (PMID 37876963, 2023). "In addition, NTRK inhibitors have shown high efficacy in multiple NTRK-driven cancers, and our case demonstrated significant clinical benefit of such therapy in the patient with NTRK2 fused sLGG." (PMID 36163281, 2022). "Similarly, upregulation of NTRK2 expression promotes cancer cell migration and invasion, which is also consistent with our predictions." (PMID 36249029, 2022). "In conclusion, our study illustrated that NTRK2 was a putative cancer suppressor gene and could serve as a promising biomarker in tumorigenesis and treatment of LUAD patients." (PMID 31245181, 2019). "Collectively, the findings observed above suggested that NTRK2 might enhance the response of cancer cells to the chemotherapeutics." (PMID 31245181, 2019). "Emerging evidence suggests that NTRK2 plays an important role in different cancers." (PMID 29306329, 2018). "Fusions of NTRK1, NTRK2, and NTRK3 and their partner genes can lead to overexpression of Trk proteins, which in turn activate downstream signaling pathways, such as RAS/MAPK, PI3K/AKT, and PLC-γ, causing transformation, proliferation, and survival of cancer cells." (PMID 41383499, 2025). "However, recent studies have demonstrated the possible role of NTRK2 in the development of cancer." (PMID 31245181, 2019). "Inhibitors such as larotrectinib, entrectinib and repotrectinib are used when cancer cells harbor NTRK1, NTRK2 or NTRK3 fusion." (PMID 41744839, 2026). "Red dots denote significantly upregulated genes, such as TP63, NTRK2, and CLCA2, highlighting their elevated expression in cancer samples." (PMID 40370696, 2025). "Rearrangements involving the neurotrophic-tropomyosin receptor kinase (NTRK) gene family (NTRK1, NTRK2, and NTRK3) have been identified as drivers in a wide variety of human cancers." (PMID 38863624, 2024). "We further integrated our methylation results with RNA-seq data, and we identified 11 genes, including six related to immune functions (AHR, LRFN5, NTRK2, RSPO2, SAMSN1, and TFEC), and three related to cancer (SLC12A5, SORCS1, and TP63)." (PMID 39795948, 2024). "These tyrosine kinase receptors have received some attention from the clinical point of view, given that NTRK gene fusions including NTRK1, NTRK2, and NTRK3 are identified as oncogenic drivers in various types of tumors, including an increase in cancer in DM1." (PMID 36767649, 2023). "Gene fusions involving NTRK1, NTRK2, and NTRK3 are rare drivers of cancer that can be targeted with histology-agnostic inhibitors." (PMID 35328221, 2022). "Chromosomal translocations involving the NTRK1, NTRK2, and NTRK3 genes result in constitutive activation and aberrant expression of TRK kinases in numerous cancer types." (PMID 32466202, 2020). "Given the abundance of literature highlighting the role of NTRK2 in cancer, we found similar whole gene NTRK2 expression across Normal Brain, LGG and GBM samples, suggesting that differences in expression of particular splice variants may underlie potential oncogenic effects driven by NTRK2." (PMID 32532995, 2020). "In neuronal cells, the cancer-related gene SLIT2 was found to be upregulated, as were six other cancer-related genes (PDGFRA, DDR2, RSPO3, IL6ST, NTRK2, and HEY1) in cardiomyocytes and one cancer-related gene (HSD3B1) in hepatocyte-like cells." (PMID 32127560, 2020).
cancer (continued). "Oncogenic fusion genes involving the NTRK family (NTRK1, NTRK2, or NTRK3) have been identified in various cancers, and a few NTRK-TKIs have been effective against the NTRK-rearrangement-positive cancers in clinical trials." (PMID 31399568, 2019). "Although the mechanisms by which the cancer cells evade anoikis are unknown, the gain of miR-200c expression in endometrial and breast cancer in cultures restored the sensitivity of these cells toward anoikis, through suppression of neurotrophic-tyrosine-receptor kinase type 2, NTRK2." (PMID 27601996, 2016). "Therefore, the differentially methylated specific genes (NTRK2, MAPKAPK2, CRK, and NFATC2) and the dysregulated miRNAs (mir-148a, mir-374a and mir-494) in the MAPK and ErbB pathways cause cell proliferation, adhesions and migration and the immune cell infiltration to cancer cells during early HCC." (PMID 27821810, 2016). "The brain-derived neurotrophic factor (BDNF) activates its receptor, tropomyosin receptor kinase B (TrkB; also called NTRK2) that has been shown to promote the malignant progression of several cancers." (PMID 27458153, 2016). "Several target genes of miR-204, including HOXA10, MEIS1, FOXC1, MAP1LC3B, BCL2, NTRK2, SOX4 and EphB2, have been identified in different cancers." (PMID 26710269, 2015). "We also detected several low-frequency, pan-cancer kinase fusion events, for example in the neurotrophic tyrosine receptor kinases NTRK1, NTRK2 and NTRK3, that drive tumorigenesis in a small fraction of multiple cancers, regardless of tissue type." (PMID 25204415, 2014). "As a result, we found that 3′-phosphoadenosine 5′-phosphosulfate synthase 2 (PAPSS2), γ-tubulin gene 2 (TUBG2), NTRK2, B4GALT1, and OSMR as well as SFRP4 harbored cancer-specific methylation with high frequencies (>30%)." (PMID 19662090, 2009). "RAC2 also showed upregulation of proliferative pathways, including signalling by NTRK2/TRKB, characterised by overexpression of the PIK3CA gene, and signalling by ERBB2 in cancer, as reflected by elevated serum concentrations of SHC1, ERBB4, EGFR and ERBB2, compared with RAC3." (PMID 39401856, 2024). "The targets of some of these genes are cancer-related genes, including BDNF, NTRK2, and MAPK3." (PMID 37100464, 2023). "The most common mechanism of Trk activation in cancer is fusion involving NTRK1, NTRK2, and NTRK3." (PMID 34209967, 2021). "In the responsive group, 9 mutations (26%) were found in genes concerning proliferation pathways: PIK3CA (2 ADC with exon 9 E545K, and a poorly differentiated carcinoma with H1047R), BRAF (V600E in 2 ADC), STK11 (V197fs 69 in one ADC and F354L in one SCC), NTRK2 (L755L in a SCC) and MET (N375S)." (PMID 25561229, 2014). "Although NTRK2 (originally identified as OncD), which encodes TRKB, is an old oncogene identified 35 years ago, no drug targeting this molecule has developed yet for cancer therapy." (PMID 29861866, 2018). "After enriching the DML (smokers vs. nonsmokers) for cancer-related genes, we found the Trk and Shp2 pathways to be differentially activated between these groups; these differences were driven by hypermethylation of the NTRK2 and NTRK3 genes in smokers." (PMID 27795744, 2016). "No statistical difference was observed in the abundance of VGFR2, PGFRA, FGFR3, ERBB2, NTRK2 and TIE2 among the healthy, non-tumorous (histologically normal) and tumorous livers from cancer patients." (PMID 36890818, 2023).
psychiatric disorder (59 papers, 2011 to 2025). A disorder characterized by behavioral and/or psychological abnormalities, often accompanied by physical symptoms. "Nevertheless, the association between NTRK2 and emotional processing observed herein provides further ground for the investigation of the role of NTRK2 in emotional processes in patients with psychiatric disorders." (PMID 26978740, 2016). "Our study demonstrates that genetic variability of NTRK2, a susceptibility gene for psychiatric disorders, is related to emotional arousal and—independently—to brain white-matter properties in healthy individuals." (PMID 26978740, 2016). "This novel finding could be beneficial in deciphering the physiological processes underlying effective antidepressant mechanisms or psychiatric disorders involving BDNF/NTRK2 signaling." (PMID 30765816, 2019). "Alternative splicing of the TRKB gene, NTRK2, generates either the full-length receptor (TRKB-FL) or a truncated isoform (TRKB-T1) that inhibits BDNF signaling and has been implicated in neurodegenerative diseases, psychiatric disorders, and cognitive impairments." (PMID 41360765, 2025). "Among them, NTRK2 and GRIN1 have been the long-studied genes in psychiatric disorders, and their downregulation in the postmortem brains of BD patients has been established." (PMID 33875800, 2021).
neurological diseases (31 papers, 2010 to 2025). "Various neurological diseases are associated with malfunction of NTRK2, including neurological diseases, cancers, obesity, and eating disorders." (PMID 32430868, 2020). "ASOs have already demonstrated clinical success in correcting splicing defects in several neurological disorders, and their application to the NTRK2 gene could provide a targeted approach to restore TRKB-FL levels." (PMID 41360765, 2025).
infection (21 papers, 2011 to 2025). The state of being infected such as from the introduction of a foreign agent such as serum, vaccine, antigenic substance or organism. "One example was infection-enhanced Bdnf-Ntrk2 signaling from AT1 cells to ECs, largely driven by Ntrk2 upregulation." (PMID 32461220, 2020). "Here, we provide evidence that neurotrophin receptor Ntrk2 (also known as TrkB) plays a role in the pathologic remodeling of the spleen that accompanies experimental Leishmania donovani-infection." (PMID 25710496, 2015). "This study expands our understanding of the pathogenesis of experimental VL and also demonstrates the potential of Ntrk2/Bdnf as targets for treatment of infection-induced vascular remodeling." (PMID 25710496, 2015). "Expression of Ntrk2 was not altered at d1 post infection, suggesting that induction of Ntrk2 was not the result of inflammatory responses that immediately follow infection." (PMID 25710496, 2015).
CNS tumours (5 papers, 2020 to 2024). "All gene fusion events identified in this study were in NTRK1or NTRK3, consistent with previous data indicating that fusions in TC very rarely occur in the NTRK2 gene, which is primarily associated with primary CNS tumours." (PMID 35333737, 2022). "Except for a paediatric spinal HGG (GBM-like) and a DIG, which harboured NTRK1 fusions, all other CNS tumours in this study exhibited NTRK2 fusion, consistent with its status as the most common NTRK family member exhibiting fusion in CNS tumours." (PMID 39014476, 2024).
NTRK2 also shares sentences with these, for which no sentence is quoted: neurodegenerative disease (70 papers); memory impairment (36); Parkinson disease (35); diabetes (24); brain diseases (21); ischemia (19); Cerebral ischemia (18); ischemic stroke (17); amyotrophic lateral sclerosis (14); injury (13); neurodevelopmental disorder (13); hepatocellular carcinoma (12); lymph node metastasis (12); brain injury (11); head and neck squamous cell carcinoma (11); pancreatic cancer (10); Wilms tumor (10); cystitis (9); mental disorder (9); cervical carcinoma (8); chondrosarcoma (8); autism spectrum disorder (7); dementia (7); myocardial infarction (7); osteosarcoma (7); post-traumatic stress disorder (7); Rett syndrome (7); Sepsis (7); spinal cord injury (7); triple-negative breast carcinoma (7).
A further 289 diseases each share a sentence with NTRK2 in 6 papers or fewer.